TNF (tumor necrosis factor)
Diseases named in the same sentence as TNF in open-access papers (continued):
Sharing a sentence is not in itself a finding about the gene and the disease.
tuberculosis (continued). "Using cytokine specific monoclonal antibodies against TNF-α, a 5-10 fold increase in reactivation of tuberculosis was observed." (PMID 24147054, 2013). "A cutoff of 17.3% of TNF-α-only cells of TEFF phenotype distinguished active tuberculosis from latent tuberculosis infection with 100% sensitivity (95% CI, 73.5–100.0) and 92.9% specificity (95% CI, 66.1–99.8)." (PMID 23966657, 2013). "Expression of CD45RA, CCR7, and CD127 on M. tuberculosis-specific T cells secreting only IFN-γ or TNF-α was lowest in those with active tuberculosis." (PMID 23966657, 2013). "Experimental models have shown that TNF-α plays an important role not only in host response against M. tuberculosis but also in the immunopathology of tuberculosis." (PMID 23251798, 2012). "The best fit model found was log(P(Tuberculosis)/P(sarcoidosis)) = 1.214 + 8.884 * IL1 + 0.075 * IFN + 0.32 * IL12p70 + 0.039 * TNF − 0.097 * IL5 − 0.015 * IL8 − 0.73 * IL13 − 0.606 * IL10 − 2.404 * IL2 − 4.231 * IL4." (PMID 22815689, 2012). "In cultures stimulated with PPD, the median and range of TNF-α level in the co-infected patients, 0 pg/mL (0 – 2295 pg/mL), was lower (p < 0.01) than in patients with only tuberculosis, which was 386 pg/mL (0 – 3847 pg/mL)." (PMID 22925731, 2012). "Unchanged or opposite effects on cytokine levels were shown in a murine model of pneumococcal pneumonia and tuberculosis in which increased TNF-α levels were observed after p38 MAPK inhibition but this effect was absent in LPS treated mice." (PMID 22848503, 2012). "IL10 acted to restrain the extent to which macrophages produced iNOS and TNF-alpha, two critical mediators of host control of tuberculosis." (PMID 22359543, 2012). "Several mechanisms are thought to play roles in the impairment of immunity against tuberculosis in patients using TNF-α antagonists." (PMID 22709461, 2012). "The frequency of reactivation of tuberculosis during anti-TNF therapy has significantly decreased with routine screening before starting treatment." (PMID 22709461, 2012). "Clearly, further studies are needed to evaluate the role of the TNFα/IL-2 expressing cells in the maintenance of long-term anti-tuberculosis cellular responses induced by BCG-containing vaccines." (PMID 22442674, 2012). "Recent studies revealed that the proportion of single-positive TNF-α Mtb-specific CD4+ T cells is a new tool for the rapid diagnosis of active tuberculosis disease." (PMID 23272100, 2012). "The usefulness of interferon-gamma (IFN-γ) release assays for tuberculosis screening before tumor necrosis factor-alpha (TNF-α) antagonists and for monitoring during treatment is a contraversial issue." (PMID 22709461, 2012). "We found significantly elevated protein concentrations of IL-10, monocyte chemoattractant protein-1 (MCP-1), IFN-γ, TNF-α and IL-6 in lungs, spleens, livers as well as sera of malaria-tuberculosis co-infected mice." (PMID 23110184, 2012). "The follow-up of patients who are being treated with TNF-α antagonists for tuberculosis is a further and important problem." (PMID 22709461, 2012). "TNF plays a critical protective role in the innate and adaptive response to tuberculosis in humans and mice." (PMID 22844476, 2012). "Previous studies comparing QTF and TST for screening latent tuberculosis before starting TNF-α antagonists suggested that these tests show good concordance in populations with low tuberculosis prevalence." (PMID 22709461, 2012). "Overall, the QTF and TST results of the rheumatology patients who had tuberculosis in the past were similar to those of the TNF-naive RA patients (50% versus 50% for QTF and 55% versus 57% for TST)." (PMID 22709461, 2012). "Anti-TNF-α treatment is an emerging cause of endogenous reactivation of M. bovis disease in elderly Dutch patients, as occurred in 2 of the recent bovine TB cases described in this article; reactivation may be slower than for M. tuberculosis infection." (PMID 21392437, 2011).
tuberculosis (continued). "Patients on anti-TNF treatment for chronic inflammatory diseases have an increased incidence of tuberculosis implicating TNF in the preservation from latent tuberculosis." (PMID 22132068, 2011). "We found in our drug-induced tuberculosis reactivation model that TNF is an absolute requirement for the containment of the re-emergence of tuberculosis reflected by the rapid propagation of mycobacteria after cessation of antibiotic treatment in TNF−/− mice." (PMID 22132068, 2011). "Two recent studies have assessed IFN-γ, IL-2 and TNF-α induction after overnight stimulation of whole blood or PBMC from patients with active tuberculosis and latently infected individuals." (PMID 21423578, 2011). "In studies of M. tuberculosis vaccines, our group recently showed that the anti-tuberculosis protective responses evoked by immunization were also related to the induction of double-positive IFN-γ/TNF-α expressing CD4 T cells." (PMID 22205939, 2011). "Tuberculosis is known to accelerate HIV disease progression because of production of cytokines like TNF-α, which increases viral replication." (PMID 21814542, 2011). "TCRαβ bearing macrophages accumulate in human tuberculosis granulomas and anti-TNF treatment of macrophages results in downregulation of the TCRαβ, which is associated with caspase 3 cleavage and suppression of TCRξ." (PMID 22114556, 2011). "In conclusion data presented here, illustrates that TNF mediated immunity against M. tuberculosis infection requires both Tm-TNF and solTNF during tuberculosis reactivation." (PMID 22132068, 2011). "The importance of TNF for maintaining latent infection was verified in clinical studies in which anti-TNF therapy administered to patients with chronic inflammatory diseases resulted in spontaneous reactivation of tuberculosis." (PMID 22132068, 2011). "In tuberculosis an elevation of the TNF-α level, stimulated by lipoarabinomanan and other lipopolysaccharides present in the cell wall, has been postulated as an initial step in the development of paradoxical reaction." (PMID 21829740, 2011). "Sustained TNF expression is required for containment of persistent infection and TNF neutralization leads to tuberculosis reactivation." (PMID 22132068, 2011). "Clinically, similar findings were noted in reactivating tuberculosis patients on anti-TNF therapy who presented with a decreased T cell activation profile and reduction in IFNγ and IL-10 synthesis." (PMID 22132068, 2011). "Treatment of latent tuberculosis infection (LTBI) in high risk groups such as those who are HIV positive or those in whom anti-TNFα therapy is to be commenced plays an important role in control of tuberculosis (TB) disease in low-TB incidence settings." (PMID 22216316, 2011). "In this study, we investigated the contribution of soluble TNF (solTNF) and transmembrane TNF (Tm-TNF) in immune responses generated against reactivating tuberculosis." (PMID 22132068, 2011). "The presence of the TCRαβ in mouse macrophages offers the possibility to study the role of the TNF/ TCRαβ/ CCL2 regulatory axis we identified in human macrophages in tuberculosis in vivo." (PMID 22114556, 2011). "In the United States, the occurrence of tuberculosis in patients on anti-TNF therapy (most commonly in the first 90 days of treatment) supports reactivation of infection as the most likely mechanism of disease." (PMID 21605439, 2011). "Tumor Necrosis Factor-alpha (TNFα) is required for the formation of protective granulomas during tuberculosis." (PMID 21249199, 2011). "Here, we report that Tm-TNF and solTNF are both required for the maintenance of immune pressure during reactivating tuberculosis." (PMID 22132068, 2011). "TNF-α levels were measured in the serum samples of 107 tuberculosis patients and 112 unrelated controls." (PMID 20537163, 2010). "And among blacks, a combination of SNPs in TNF-α and TLR4 predicted tuberculosis risk with 71% accuracy." (PMID 20196868, 2010).
tuberculosis (continued). "A decrease of the tuberculosis-specific CD4pos T-cell response in patients treated with anti-TNF was found." (PMID 20633267, 2010). "Of these, TNF-α contributes to the pathogenesis of tuberculosis due to its role in the formation and maintenance of granulomas." (PMID 20537163, 2010). "Elevated serum TNF-α (sTNF-α) levels have been reported in advanced tuberculosis patients when compared to those with mild tuberculosis and healthy individuals." (PMID 20537163, 2010). "The main objective of RATIO was to collect in an exhaustive way all over the country two rare side effects of TNFα blockers, which are opportunistic infections (including tuberculosis) and lymphomas." (PMID 20637100, 2010). "Additional studies are required to evaluate the safety and efficacy of continuing TNF-α inhibitors during tuberculosis therapy." (PMID 19830122, 2009). "Other reports suggest, however, the maintenance of low doses of a TNF-α inhibitor or to continue the TNF-α inhibitor therapy during treatment of active tuberculosis; at present, the safety implications of either approach are unclear." (PMID 19830122, 2009). "TNF-α, an inflammatory cytokine expressed by activated macrophages, T-cells and other immune cells, plays a crucial role in host responses against tuberculosis, including granuloma formation and inhibition of dissemination." (PMID 19830122, 2009). "The current recommendation is for the discontinuation of TNF-α inhibitors in patients during treatment for active tuberculosis; this is mandatory for those patients with proven mycobacterial infections." (PMID 19830122, 2009). "The anti-inflammatory capacity of p38 is further demonstrated in mouse models of pneumococcal pneumonia and tuberculosis where its inhibition results in impaired bacterial clearance and increased TNF-α production both in vitro and in vivo." (PMID 20011115, 2009). "The risk of incident tuberculosis (TB) in patients latently infected with M. tuberculosis increases substantially, from 4 to 5 fold over baseline in the case of infliximab, after initiation of anti-TNF therapy." (PMID 18706526, 2008). "A marked increase in opportunistic infections, particularly tuberculosis, has been described with etanercept, an agent that blocks TNF-alpha activity." (PMID 18662412, 2008). "In contrast to the TNFα inhibitors, infective complications including tuberculosis and opportunistic infections are much less common with rituximab." (PMID 19088893, 2007). "Increased levels of CCL2, CXCL8 and TNFα are reported in tuberculosis but their significance in different forms of tuberculosis is as yet unclear." (PMID 16001981, 2005). "To ascertain the role of soluble vs membrane-bound TNF in resistance to tuberculosis, we compared mem-TNF, TNF-KO mice and WT mice infected with 100 CFU Mtb given by intranasal administration." (PMID 16285886, 2005). "However, patients treated with immunosuppressive agents for irAEs, such as corticosteroids or tumor necrosis factor (TNF) inhibitors, are at higher risk for opportunistic infection and tuberculosis reactivation." (PMID 40145913, 2025). "Over time, granulomas may evolve into fibrotic or necrotic lesions, with necrosis being particularly prominent in tuberculosis due to tumor necrosis factor alpha (TNF-α)–mediated apoptosis." (PMID 40837573, 2025). "Therefore, we conducted PPI network analysis on the TNF signaling pathway genes and Tuberculosis pathway genes, and obtained important pathway gene modules for each pathway." (PMID 40725488, 2025). "Active tuberculosis developed during TNF inhibitor therapy in 12 bioexperienced patients." (PMID 40806803, 2025). "Only a few cases of tuberculosis under anti-TNFα treatment have been described worldwide." (PMID 40851998, 2025). "Therefore, for patients suspected of having latent or active pulmonary tuberculosis, anti-TNF-α therapy should be deferred, and anti-tuberculosis treatment should be carried out according to national guidelines." (PMID 40763141, 2025).
tuberculosis (continued). "Their abnormal expression may affect the DCs’ immune response to M.tb through the TNF signaling pathway, and they may also be related to the Tuberculosis pathway." (PMID 40725488, 2025). "In patients with LTBI or previously treated tuberculosis, etanercept rather than other TNF inhibitors is recommended to reduce the risk of tuberculosis infection." (PMID 39070789, 2024). "Patients starting anti-TNF-α therapy were classified as high-risk, and it was recommended to use the tuberculin skin test, interferon-gamma release assay, or both to rule out tuberculosis before beginning the regimen." (PMID 39310504, 2024). "Together, the pathways identified here overlap with those identified previously in other studies of JD genetics, including the NOD-like receptor signaling pathway, phagosome, tuberculosis, NF-kappa B signaling, Toll-like receptor signaling, TNF signaling, Wnt signaling, and IL-17 signaling." (PMID 39062990, 2024). "What evidence is currently available, however, suggests that the risk of tuberculosis reactivation by most non-TNF-a inhibitors is not likely significant." (PMID 39356910, 2024). "Furthermore, NO2 can weaken the immune system by inducing the production of tumor necrosis factor alpha (TNF-α) and interferon gamma (IFN-γ), thereby increasing the susceptibility to tuberculosis." (PMID 39765608, 2024). "Interestingly, an earlier study reported nearly identical changes in a model of tuberculosis (TB) infection with TNF KO mice, in agreement with our findings." (PMID 39044282, 2024). "Moreover, recent publications have shown an increased prevalence of cutaneous T-cell lymphoma and tuberculosis in patients undergoing TNFα inhibitor therapy." (PMID 39204132, 2024). "Further, DGEA and gene ontology (GO) enrichment suggest that cluster ST10, predominantly observed during early infection, is associated with pro-inflammatory signaling (e.g., IL-17 and TNF pathways), including phagocytosis, and KEGG-terms including leishmaniasis and tuberculosis." (PMID 39160174, 2024). "The TNF signaling pathway is highly enriched, leading us to speculate that it may be the primary signaling pathway mediating the anti-tuberculosis effects of GJZLP." (PMID 39015338, 2024). "TNF inhibitors increased the risk of tuberculosis but not that of opportunistic infections and herpes zoster." (PMID 39070789, 2024). "TNF-α recruits innate immune cells, such as monocytes and granulocytes, to the site of infection and contributes to the formation of tuberculous granulomas in infected tissues, which helps to prevent the spread of tuberculosis bacteria in the body." (PMID 38741147, 2024). "For example, tumor necrosis factor (TNF)-α inhibitors may lead to tuberculosis reactivation, and anti-CD20 targeted therapy may lead to hepatitis B virus (HBV) reactivation." (PMID 39273134, 2024). "Lc intervention decreased alkaline phosphatase (ALP), superoxide dismutase (SOD), glutathione (GSH), malondialdehyde (MDA), and tumor necrosis factor (TNF)-α levels (p < 0.05), recovered hepatic lobules, and reduced hepatocyte necrosis to alleviate liver injury induced by anti-tuberculosis drugs." (PMID 37298396, 2023). "In addition, it was confirmed that metformin increased proinflammatory cytokines (TNF-α, IL-1α, IL-1β, IL-6, IL-18, IL-8, and IFN-α) in Mycobacterium tuberculosis (causative agent of tuberculosis)-infected macrophages." (PMID 37700364, 2023). "Furthermore, biologic agents, exemplified by anti-TNF drugs, introduce an elevated vulnerability to infections among UC patients, concurrently posing risks of diverse tuberculosis manifestations." (PMID 37904100, 2023). "Our results, in which the occurrence of MDR-TB was more frequent in the case of longer use of infliximab, support the hypothesis that the risk of developing resistant tuberculosis might increase when TNF-α is continuously suppressed." (PMID 37035321, 2023).
tuberculosis (continued). "The combined use of BCG and M72 induced a potent anti-tuberculosis cytokine profile in cynomolgus monkeys, mainly IFN-γ, TNF-α, IL-2, and IL-6, which enabled the challenge animals to achieve long-term survival and reverse the outcome of tuberculosis progression." (PMID 37841250, 2023). "Moreover, a time-dependent decrease in the cytokine levels interferon-γ (IFN-γ) and tumor necrosis factor-α (TNF-α) was detected with tuberculosis treatments, which correlated with [125I]DPA-713 uptake." (PMID 38139248, 2023). "Therefore, we predicted central DEGs in the PPI network and noted strong interactions between TNF, IL-6, IL-10, IL-1β, CSF-2, IL-4, CXCL8, IFN-γ, IL-1α, and CXCL1, all of which are strongly associated with tuberculosis." (PMID 37818041, 2023). "The relative excess of TNF-α and IL-1β, associated with soluble TNF-α receptor secretion imbalance, was also demonstrated by these authors to be related to the pulmonary cavities in individuals with active tuberculosis (TB)." (PMID 37007342, 2023). "Combined with our transcriptomic sequencing results, we hypothesize that Mtb-Ag up-regulates PTGS2 by activating the IL-17, TNF, and NF-κB signaling pathways, making the immune response an important tool against tuberculosis." (PMID 37818041, 2023). "IL-1 and TNF-α are known to be critical for the control of tuberculosis." (PMID 37764917, 2023). "Thus, there are no other options for treatment with biologics for patients with primary nonresponse to anti-TNF drugs or with contraindications for anti-TNF use, such as neoplasms, tuberculosis, and congestive heart failure." (PMID 37048755, 2023). "Tuberculosis was found to be more frequent with both tofacitinib doses than with an anti-TNF." (PMID 37835065, 2023). "Although there was no consensus on the risk of infection associated with anti-TNFα treatments in published clinical trials, post-marketing surveillance and retrospective studies have shown an increased risk of tuberculosis and other granulomatous infections." (PMID 37554981, 2023). "IFN-γ and TNF-α were significantly higher among tuberculosis positive patients." (PMID 35198736, 2022). "Tumor necrosis factor (TNF) is a critical host resistance factor against tuberculosis." (PMID 35737799, 2022). "However, there were specific variations in the incidence of tuberculosis reactivation between the individual TNF blockers." (PMID 36036323, 2022). "Here, using the zebrafish, we identify the mechanism of TNF-induced mROS in tuberculosis." (PMID 35737799, 2022). "Evidence exists for metformin use in treatment of both tuberculosis and rheumatological diseases, suggesting that metformin may even be a safer alternative to TNF inhibitors." (PMID 36159650, 2022). "Nevertheless, clinical pan-TNF intervention leads to concerns of the off-target effect (e.g., fever, hypotension, tuberculosis, and malignancy) as the TNF signaling pathway is a master regulator of innate immunity, and TNFR1 is expressed widely in most cell types." (PMID 35387335, 2022). "Due to the occurrence of tuberculosis cases in the early years of TNF blocker treatments, physicians were sensitized to this issue, which is why LTBI often became a reason for exclusion in approval studies for newer bDMARDs and tsDMARDs or LTBI was treated preventively." (PMID 36036323, 2022). "In our study, six weeks of anti-tuberculosis drugs had elevated the TNF-α level." (PMID 35458230, 2022). "It was reported that TNF monoclonal antibodies may more strongly inhibit granuloma formation in tuberculosis as compared with etanercept." (PMID 34552481, 2021). "Moreover, miR-23a-3p was shown to inhibit monocyte function and phagocytosis by targeting IRF1/SP1 followed by the TLR4/TNF-α/TGF-β1/IL-10 signaling pathway in patients with active tuberculosis." (PMID 34608568, 2021). "Importantly, TNF, which drives the pathogenesis caused by LTA4H excess in the zebrafish model of tuberculosis is significantly increased in TT patients." (PMID 33658385, 2021).